NBR1 (NBR1 autophagy cargo receptor)
Diseases named in the same sentence as NBR1 in open-access papers (continued):
Sharing a sentence is not in itself a finding about the gene and the disease.
infection (18 papers, 2013 to 2024). The state of being infected such as from the introduction of a foreign agent such as serum, vaccine, antigenic substance or organism. "Selectivity is mediated by autophagy receptors, of which p62 and NBR1 play key roles in controlling pathogenic infection in mammals." (PMID 35620914, 2022). "Infection with Xcv resulted in an induction of NBR1/Joka2 bodies in comparison to Xcv ΔxopL infected leaves." (PMID 35620914, 2022). "In fact, ubiquitinated proteins are observed to hyperaccumulate in nbr1 or atg5 mutants upon infection conditions shown to induce autophagy." (PMID 35635102, 2022). "While we investigated the effect of Xcv and its T3E XopL on host autophagy, we noticed that NBR1/Joka2 responds at both transcript and protein levels during infection." (PMID 35620914, 2022). "The type-III effector XopL can interact with the autophagy component SH3P2 through E3 ligase activity and degrade it to promote infection, while XopL is degraded by NBR1-mediated selective autophagy." (PMID 36232711, 2022). "Cells infected with RABV had significantly higher expression levels of LC3-II, p62, and NBR1 (an autophagy cargo protein) than cells with mock infection." (PMID 34113320, 2021). "This is illustrated by AGO2, CABBP1, and NBR1 genes, which produce vasiRNAs upon infection likely to regulate the levels of their transcripts." (PMID 33230160, 2020). "The high amounts of secondary siRNAs produced from NBR1 during infection correlated with high transcript levels as previously shown with AGO2." (PMID 33230160, 2020). "In our ex vivo infection assay it was also observed that activation of autophagy by rapamycin treatment decreased p62/NBR1 in B. pseudomallei infected human PBMCs." (PMID 30569531, 2019). "In our ex vivo infection assay it was observed that activation of autophagy by rapamycin treatment decreased p62/NBR1 in B. pseudomallei infected human PBMC." (PMID 30569531, 2019). "Further, we tested the effect of CLCuMuV infection on autophagy flux using Joka2/NBR1, a selective autophagy cargo receptor, as a protein marker." (PMID 28244873, 2017). "Notably, expression of NBR1 displayed a high positive log fold change during infection with P. syringae pv." (PMID 35635102, 2022). "In addition, infection by the double-stranded DNA pararetrovirus cauliflower mosaic virus (CaMV) also mediates its degradation through NBR1-regulated selective autophagy." (PMID 36232711, 2022). "These contrasting phenotypes might be related to the dual roles of autophagy during the infection of Pst, whose effectors can exploit autophagy for proteasome degradation and enhanced virulence, and can also be targeted by NBR1 for autophagic suppression." (PMID 35563184, 2022). "Our in vitro data in a cell‐culture based infection assays demonstrated that induction of autophagy with rapamycin treatment reduced intracellular p62 /NBR1 and bacterial survival in J774.1 cells infected with B. thailandensis, a correlation of p62/NBR1 with bacterial survival." (PMID 30569531, 2019). "During the infection of cauliflower mosaic virus (CaMV), host autophagy is also activated to guide the vacuolar degradation of the viral capsid protein P4 in an NBR1-dependent manner via the direct binding of NBR1 to P4, by which CaMV initial infection is suppressed." (PMID 35563184, 2022). "Intriguingly, relative mRNA levels of both NBR1 and CALCOCO2 (NDP52) significantly increased at the late infection time point, specifically at 18 hpi." (PMID 39120287, 2024). "Of note, infection by T. gondii significantly inhibited starvation-induced transcription of autophagy-related genes (i.e., ULK1, BECN1, PINK1, GABARAPL2, SQSTM1, and NBR1), as compared to uninfected serum-starved HFF cultures (i.e., “Control”)." (PMID 37387601, 2023).
infection (continued). "Two recent publications have provided strong evidence that two ATGs, i.e., NBR1 and ATG8 can function as cargo receptor proteins to selectively interact with viral proteins to mediate their degradation and defend infection from two DNA viruses." (PMID 29593293, 2018). "We have found that shortly after infection the PVM in the vast majority of P. berghei-infected cells is decorated with the autophagy receptor proteins p62 and NBR1 and to a much lesser extent with NDP52." (PMID 28841718, 2017). "However, the overexpression of NBR1 AAV alleviated these symptoms, and this beneficial effect was impeded by simultaneous infection with NBR1 and SRBD1 AAVs." (PMID 38169523, 2024). "In the present study, the level of NBR1 protein was found to be elevated in wax moth hemolymph after fungal invasion, while p62 protein level remained stable, even after infection; it is possible that autophagy took place without the need for p62 protein." (PMID 32012188, 2020). "Unlike atg5 and atg7 mutants, nbr1 mutants were normal in age- and dark-induced senescence and in response to necrotrophic pathogen infection." (PMID 23341779, 2013). "In the same study, it was also shown that knockdown of NBR1 expression via virus-induced gene silencing (VIGS) reduced Xcv growth at 3 days-post-inoculation (dpi) compared with WT but not at 6dpi, thus indicating for a role in selective autophagy during the earlier steps of infection." (PMID 35635102, 2022).
cancer (12 papers, 2017 to 2025). A tumor composed of atypical neoplastic, often pleomorphic cells that invade other tissues. "While the role of NBR1 in cancer remains uncertain, decreased NBR1 mRNA levels have been correlated with unfavorable outcomes in ccRCC." (PMID 39596452, 2024). "A higher level of LINC01592/E2F6/NBR1 expression was detected in cancer tissues, especially in III + IV." (PMID 37915049, 2023). "Data from the Human Protein Atlas show that NBR1 mRNA is expressed in most cancers with low-cancer specificity." (PMID 36255390, 2022). "The expression of NBR1 mRNA shows low cancer specificity, and there are weak to moderate NBR1 protein level in cytoplasm of different cancer cells." (PMID 34926299, 2021). "Although the clinical data available show a negative association between the NBR1 mRNA levels and the prognosis of patients with cancer, other findings suggest a positive contribution of NBR1 in the acquisition of pro-tumorigenic properties." (PMID 33634029, 2020). "Related to cancer prognosis, it has been reported that low mRNA levels of NBR1 predict a poor clinical outcome in patients with clear cell renal carcinoma." (PMID 33634029, 2020). "It is also found in direct or indirect interactions with numerous known cancer genes, such as NBR1, BRACA1, ICT1, SUMO, NUP85 and others." (PMID 31142264, 2019). "For example, Nbr1 and p62 which both function as pexophagy receptors, play a role in cancer homeostasis." (PMID 30250843, 2018). "Additional involvement of Nbr1 and p62 to cancer metabolism is indicated through their responsiveness to several compounds with anticancer properties." (PMID 30250843, 2018). "NBR1 mRNA expression in ccRCC cancer tissues and normal tissues was assessed from TCGA-KIRC database which contained 533 cases including 72 paired cases." (PMID 29212269, 2017). "NBR1 is recognized as a regulator of diverse cellular kinase signaling pathways with multiply domains now and its role in cancer need more attention." (PMID 29212269, 2017). "Lastly, roles of NBR1 in human diseases such as proteinopathies and cancer are emerging." (PMID 36255390, 2022). "There has been little information about the role of NBR1 in cancer." (PMID 34926299, 2021). "However, other findings revealed the properties of NBR1 in promoting cancer migration and metastasis, and in inducing tumor immune escape by distributing major histocompatibility complex-I (MHC-I) on the cell surface." (PMID 34926299, 2021). "Little information is known about the role of NBR1 in cancer." (PMID 33634029, 2020). "Contrary, silencing of NBR1 suppresses cancer dissemination." (PMID 33634029, 2020). "Moreover, the mRNA level of NBR1 was able to classify ccRCC patients with a good or poor prognosis both in cancer tissues and normal tissues." (PMID 29212269, 2017). "Additionally, how NBR1 is regulated and plays different roles in cancer cell motility and metastases outgrowth and whether NBR1 is involved in other cancers need further investigation." (PMID 34829881, 2021). "Therefore, the role of NBR1 in cancer is complicated and needs further investigations." (PMID 34926299, 2021). "The investigation conducted has revealed a significant molecular interaction between TAMs and EC via the LINC01592/E2F6/NBR1/MHC-I axis, which facilitates the progression of malignant tumors." (PMID 37915049, 2023). "The TCGA database analysis also revealed that expression of NBR1 and E2F6 is elevated in cancer tissues, and their expression was inversely related to patient outcome." (PMID 37915049, 2023). "More studies are required to probe for possible direct or indirect roles of NBR1 and other SLRs on the turnover of MHC class I in different normal and cancer cells." (PMID 36255390, 2022). "In this review, we summarized the most important findings related with the pro-tumorigenic role of autophagy receptors p62/SQSTM1, NBR1, NDP52, and OPTN in cancer progression." (PMID 33634029, 2020).
cancer (continued). "Finally, to prove that the increased cancer cell death upon knockdown of circGRAMD4, RBM4 and NBR1 is mediated by increased MHC-I expression on cancer cells, cell surface MHC-I was depleted by knocking down B2M, a critical component of the MHC-I complex." (PMID 40373256, 2025). "In vivo, the mice in the model groups displayed cancer progression, and the expression of some of the autophagy-related genes, DRAM1, NBR1, ATG7, MAP1LC3A were also increased in mice given F. nucleatum or F. nucleatum with L-cysteine when compared to the untreated control mice." (PMID 37889013, 2023). "According to IHC results of CD8+ in animal transplanted cancer samples, mice in the LINC01592-OE groups expressed obviously less CD8+; however, the phenomenon could be reversed by knocking down NBR1 while overexpressing LINC01592." (PMID 37915049, 2023). "In recent years, several comprehensive studies have revealed potentially unique roles for NBR1 in cancer development, independent of p62." (PMID 36255390, 2022). "Interestingly, several cytosolic autophagy receptors such as p62/SQSTM1, NBR1, NDP52 and OPTN have been reported to be overexpressed in several types of cancer playing regulatory roles in the last stage of carcinogenesis." (PMID 33634029, 2020). "NBR1 mRNA expression of cancer tissues and normal tissues in non-recurrent ccRCC was significantly higher in recurrent ccRCC." (PMID 29212269, 2017). "However, these deletions, which usually contain BRCA1, NBR2, BRCA1P1, and NBR1 genes, are not restricted to the NBR2 gene, and further studies are needed to confirm whether a specific deletion of the NBR2 gene determines cancer susceptibility." (PMID 34926299, 2021).
Bacterial Infection (3 papers, 2020 to 2025). "The authors suggested that NBR1 contributes to the turnover of ubiquitylated substrates that were hyperaccumulated during bacterial infection." (PMID 36768543, 2023). "Interestingly, NBR1-dependent selective autophagy, albeit activated by bacterial infection, counteracts disease progression." (PMID 36768543, 2023).
neurodegenerative disease (3 papers, 2022 to 2025). A disorder of the central nervous system characterized by gradual and progressive loss of neural tissue and neurologic function. "Studies have found that Nbr1 is highly expressed in a variety of neurodegenerative diseases, and aberrant regulation of p62 has been shown to cause multiple neurodegenerative diseases." (PMID 39912396, 2025). "In many cases of patients of neurodegenerative diseases including CLNs, PD, and AD, ubiquitin-positive signals and autophagy-related proteins (p62, Nbr1, LC3) accumulate in the brain." (PMID 35804072, 2022). "NBR1 was shown to colocalize with α-synuclein in Lewy bodies in PD brains, but not with other aggregated proteins in neurodegenerative diseases." (PMID 37315142, 2023).
myopathy (2 papers, 2007 to 2013). A disease of the muscle in which the muscle fibers do not function properly. "VCP was increased by 139.7%, HDAC6 by 98.6%, p62 by 124.8% and NBR1 by 149.2% (P<0.05) in GNE myopathy patients." (PMID 23472144, 2013).
neurological disease (2 papers, 2019 to 2025). "The SC2disease database was used to analyze the association of Nbr1 and Dph3 with neurological diseases." (PMID 39912396, 2025). "Dph3 and Nbr1 are closely related to neural development and neurological diseases." (PMID 39912396, 2025). "SFN is located at the center of an interaction network of proteins including HYAL2, NBEA, NBR1, AURKAIP1, RALGPS2, and SLC1A2, some of which have known involvement in brain function and neurological disease." (PMID 31029150, 2019).
muscular disorder (1 paper, 2016). "However, although a mutation in titin disrupting nbr1 interactions with the kinase domain of titin is associated with a muscular disorder, there are no specific models of NBR1 disruption with an overt muscle phenotype." (PMID 27484057, 2016).
neuromuscular disease (1 paper, 2020). "In particular, NBR1 is involved in ensuring ubiquitinated protein degradation, whose inappropriate aggregation is a common feature to numerous neurodegenerative and neuromuscular diseases." (PMID 33043004, 2020).
NBR1 also shares sentences with these, for which no sentence is quoted: C3 glomerulopathy (1 paper); Glucose intolerance (1); Hypertension (1); Insulin resistance (1); leukemia (1); lymph node metastasis (1); multiple system atrophy (1); myotilinopathy (1); nematode infection (1); nutritional deficiency (1); psychiatric disorder (1); Sepsis (1); Stroke (1).